GLS (glutaminase)
Diseases named in the same sentence as GLS in open-access papers (continued):
Sharing a sentence is not in itself a finding about the gene and the disease.
ovarian carcinoma (continued). "In three independent publicly available microarray datasets of ovarian cancer patients, we found a significant correlation between higher levels of glutaminase gene expression and reduced progression free and overall survival." (PMID 27191653, 2016). "Recent studies have highlighted the role of glutamine metabolic pathways in ovarian cancer progression and high glutaminase (GLS) expression in human tissue samples has been shown to be associated with poor survival." (PMID 27191653, 2016). "We next investigated the impact of glutamine on GLS protein expression using different levels of glutamine in our ovarian cancer cells." (PMID 26045471, 2015). "Interestingly, inhibition of glutaminolysis by the glutaminase inhibitor CB-839 sensitized ovarian cancer cells to PP242 treatment, the same mTOR inhibitor which also blocked C. parvum infection in this study." (PMID 41156614, 2025). "Ovarian cancers refractory to standard platinum-based chemotherapy may benefit from treatment with this glutaminase inhibitor, and the results of clinical trials are pending." (PMID 37985723, 2023). "Therefore, the JAK-STAT signaling pathway can indirectly regulate the expression of glutaminase through the oncogene myc and play an important role in the metabolism of ovarian cancer cells." (PMID 36523985, 2022). "Increased dependence on glutamine metabolism through the upregulation of glutamine transporters ASCT2 and GLS was also observed in cisplatin-resistant ovarian cancer cells, which were more sensitive to glutamine deprivation by GLS knockdown as compared to their cisplatin-sensitive counterparts." (PMID 33804114, 2021). "Indeed, co-inhibition of glutamine synthetase (GLUL) in CAFs and glutaminase (GLS) in ovarian cancer cells abrogated cancer cell growth better than each individual treatment." (PMID 33540679, 2021). "In conclusion, our findings provide a novel insight into ovarian cancer cells influence the immune system in the tumor microenvironment and highlight the potential clinical implication of combination of immune checkpoints with GLS inhibitor 968 in treating ovarian cancer." (PMID 34944392, 2021). "Our collective findings revealed that the increased T cell function and infiltration into tumors in response to compound 968, and the inhibition of glutaminase by compound 968, helped to improve the treatment effect of immune checkpoint blockade in ovarian cancer." (PMID 34944392, 2021). "Indeed, works on lung and ovarian cancer showed that invasive phenotype strongly relies on the expression of glutaminase." (PMID 32932943, 2020). "Furthermore, the combination of glutaminase inhibitors with chemotherapy agents also increased sensitivity of cancer cells to chemotherapy in pancreatic cancer and ovarian cancer." (PMID 33194749, 2020). "Interestingly, the inhibition of glutaminase synergizes with cisplatin treatment, ultimately leading to increased ovarian cancer cell apoptosis." (PMID 32932943, 2020). "First, glutaminolysis could be targeted by glutaminase inhibitors, such as the small inhibitor CB-839, that already showed promising results in resistant myeloma, esophageal carcinoma, and ovarian cancer." (PMID 32455924, 2020). "In an orthotopic mouse model for ovarian carcinoma, the simultaneous depletion of glutamine synthetase (GS), upregulated in CAFs during metabolic coupling, and glutaminase (GLS), expressed in cancer cells, results in a greater reduction of tumour growth and metastasis with respect to monotherapy." (PMID 29967776, 2018). "Further studies are needed to determine whether the observed synergistic effect of glutaminase inhibition in ovarian cancer is specific to platinum chemotherapy." (PMID 27191653, 2016). "Targeting GLS, a key enzyme in glutamine metabolism, through genetic knockdown or pharmacological inhibition (e.g., using CB-839) can induce glutamine deprivation and ROS accumulation in cancer cells, subsequently triggering ferroptosis in ovarian cancer cells." (PMID 41462613, 2025).
ovarian carcinoma (continued). "Furthermore, we found that the anti-PD-L1 antibody could enhance the antitumor response when combined with glutaminase inhibitor compound 968 in the syngeneic murine model of ovarian cancer." (PMID 34944392, 2021). "Increased expression of glutaminase and the glutamine transporter SLC1A5/ASCT2 has been observed in cisplatin-resistant ovarian cancer cells, and the inhibition of ASCT2 and glutaminase has been shown to sensitize these cells to cisplatin." (PMID 37233659, 2023). "Significantly, the combination of GLS inhibitor (BPTES) and platinum can synergistically inhibit platinum-sensitive and resistant ovarian cancer in vitro." (PMID 36523985, 2022). "Lately, it has been shown that miR-145 inhibits glutaminolysis in ovarian cancer cells by decreasing the expression of c-MYC, which lowers GLS transcription." (PMID 36483029, 2022). "The activities of IDH, KGDH, SDH, GLS and other related enzymes are often enhanced, while the activities of SSDH and GS are decreased in ovarian cancer." (PMID 34796116, 2021). "Co-targeting GS in CAFs and glutaminase in cancer cells disrupted CAF/tumor cell metabolic crosstalk, inducing tumor regression in an ovarian carcinoma mouse model." (PMID 34373744, 2021). "Concomitant upregulation of glutaminase (GLS) and c-MYC has been observed in platinum-resistant ovarian cancer cells." (PMID 33718147, 2021). "Furthermore, we found that compound 968, as an inhibitor of glutaminase, was able to inhibit cell proliferation, which was consistent with the findings of Yuan and co-workers who reported that compound 968 inhibited cell proliferation and sensitized cells to paclitaxel treatment in ovarian cancer." (PMID 34944392, 2021). "As case study, we quantified expression of MCT1, MCT4, GLS, PHGDH, FAS, and ACC in 17 patient-derived ovarian cancer xenografts and correlated it with survival." (PMID 32974128, 2020). "To validate the clinical relevance of our findings, we analyzed the relationship between glutaminase and glutamine transporter ASCT2 expression levels and outcome of ovarian cancer patients using the PrognoScan database." (PMID 27191653, 2016). "Inhibition of GLS also promotes the differentiation and effector functions of CD4+ Th1 and CD8+ CTL cells, while enhancing tumor sensitivity to radiotherapy, demonstrating that targeting GLS represents a potential strategy for ovarian cancer treatment." (PMID 41462613, 2025). "The poor prognosis in ovarian cancer patients with GLS expression was, however, not in agreement with the GENT database which showed the downregulation of this gene." (PMID 30871151, 2019). "Importantly, combining the glutaminase inhibitor BPTES with platinum synergistically inhibited platinum sensitive and resistant ovarian cancers in vitro." (PMID 27191653, 2016).
pancreatic cancer (41 papers, 2016 to 2025). "Though previous studies have evaluated efficacy of glutaminase inhibitors in cancers such as triple negative breast cancer, acute myeloid leukemia and pancreatic cancer, glutamine dependency in NF1 associated malignancies has not been studied before." (PMID 29212209, 2017). "We show that despite marked early effects on in vitro proliferation caused by GLS inhibition, pancreatic cancer cells have adaptive metabolic networks that sustain proliferation in vitro and in vivo." (PMID 28671190, 2017). "Notably, whereas both high and low expression of GLS resulted in a poor prognosis in gastric, blood, and liver cancer, the same expression pattern was associated with low survival in bladder and pancreatic cancer." (PMID 30871151, 2019). "However, an earlier study performed in pancreatic cancer showed the limited clinical efficacy of CB-839 monotherapy which highlights again that various GLS-1 inhibitors may cause significantly different effects on chromaffin cells’ proliferation." (PMID 32150977, 2020). "Recent studies in pancreatic cancer cells have shown that GLS expression is induced in response to nutrient deprivation, and that GLS hyperactivation promotes metabolic reprogramming and cancer progression." (PMID 40711148, 2025). "Zaprinast lowers pyruvate driven OXPHOS in isolated mice brain mitochondria and GLS activity in pancreatic cancer cells." (PMID 38350962, 2024). "Recent studies have evidenced that KRAS-driven lung and pancreatic cancer with KEAP1 or NRF2 mutations are highly dependent on glutaminolysis and are vulnerable to glutaminase inhibition." (PMID 38830868, 2024). "Using affinity chromatography, immunoprecipitation, and mass spectrometry techniques, we unveiled an interaction between ERK5 and the mitochondrial glutaminase GLS in pancreatic tumor cells." (PMID 38542254, 2024). "We next explored the effect of combination treatment with TRAIL and BPTES, an inhibitor of glutaminase, a key enzyme in Gln metabolism, in vitro as well as in vivo in an orthotopic pancreatic tumor mouse model." (PMID 38684915, 2024). "α-ketoglutarate (α-KG) derived from the glutaminase-based catabolism of glutamine provides fuel for the tricarboxylic acid cycle (TCA) in pancreatic cancer cells." (PMID 37152291, 2023). "Here, we provide reliable evidence that pancreatic cancer requires TFEB for maintaining glutaminase-mediated glutamine metabolism, and that this is an attractive new target for pancreatic cancer therapy." (PMID 33513833, 2021). "Pancreatic cancer cells treated with GLS inhibitor CB-839 induce a robust oxidative stress with increases of ROS at an early time point of treatment." (PMID 33477430, 2021). "In this study, we observed increased sensitivity to glutaminase inhibition in pancreatic cancer cell lines harboring the active forms of K-ras and Nrf2." (PMID 33672789, 2021). "Glutaminase inhibition also sensitized pancreatic cancer cells to gemcitabine, the conventional chemotherapeutic agent." (PMID 33672789, 2021). "In vivo, combined inhibition of eIF4A and glutaminase exhibited an additive effect and suppressed pancreatic tumour growth in an orthotopic transplant model." (PMID 31723131, 2019). "In this study, the glutaminase II pathway is found to be upregulated for glutamate production upon GLS1 inhibition in pancreatic tumors." (PMID 31231915, 2019). "In summary, the uncovering of the role of the glutaminase II pathway as a source of the carbon backbone of glutamate upon single‐therapy GLS1 inhibition unveils the therapeutic potential of the glutaminase II pathway for the treatment of pancreatic cancer." (PMID 31231915, 2019). "Pancreatic cancer cells have a compensatory metabolic network for GLS inhibitors." (PMID 37924140, 2023).
pancreatic cancer (continued). "However, another study found that CB-839 showed an early effect in pancreatic cancer cells, but the tumor cells soon adopted an adaptive metabolic network to maintain glutamine metabolism and proliferation in a GLS-independent manner." (PMID 37924140, 2023). "In pancreatic cancers, adipocytes downregulate glutaminase to secrete and transfer glutamine under glutamine-deprived conditions, and the glutamines may reflect catabolism of lipid stores." (PMID 36503580, 2022). "In addition to combination therapy with a conventional chemotherapeutic agent, metformin—an antidiabetic agent affecting glucose metabolism—has been tested in pancreatic cancer in combination with glutaminase inhibitor." (PMID 33672789, 2021). "We need to evaluate whether these agents also enhance the antitumor effects of glutaminase inhibitors in pancreatic cancer cells, both in vitro and in vivo." (PMID 33672789, 2021). "Therefore, our data highlight the therapeutic potential of targeting miR-135 in combination with glutaminase inhibitors to enhance the treatment of pancreatic cancer." (PMID 30778058, 2019). "Furthermore, glutaminase inhibitors sensitize pancreatic cancer cells to PARP-driven cytotoxic effects on PDAC cells." (PMID 29156578, 2017). "Interestingly, GLS inhibition significantly decreased CFPAC-1 survival suggesting that pancreatic cancer cells, known to have specific addiction to glutamine, are markedly more sensitive to GLS inhibition when ENO1 function is impaired." (PMID 26734996, 2016). "Then, the upregulated LDHB could activate glycolysis and decrease GEM sensitivity in pancreatic cancer, and the increased glutamine synthetase and decreased glutaminase could further increase the level of intracellular glutamine, which is indispensable for mTOR activation." (PMID 30419950, 2018). "In pancreatic cancer, the transcription factor EB (TFEB) is required to sustain GLS-dependent glutamine catabolism; therefore, it has been proposed as a new potential therapeutic target." (PMID 38542254, 2024). "Don and azaserine, two glutaminase inhibitors, decreased the level of CA19-9 in pancreatic cancer cells." (PMID 36797531, 2023). "Coadministration of a glutaminase inhibitor with gemcitabine also abrogated MUC5AC (Mucin 5AC)-mediated gemcitabine resistance in mouse and human pancreatic cancers, providing a new target for future immunotherapy." (PMID 35515122, 2022). "Gemcitabine, one of the main chemotherapeutics used to treat pancreatic cancer, did not elicit the same effect, demonstrating the selective sensitivity of CR-31-treated cells to the inhibition of glutaminase." (PMID 31723131, 2019). "The pancreatic cancer cell line BxPC3—harboring wildtype K-ras—could not be further sensitized to glutaminase inhibition." (PMID 33672789, 2021). "GLS inhibition significantly decreased CFPAC-1, but not MDA-MB-231 or NCI-H441 cell survival, suggesting that pancreatic cancer cells are considerably more sensitive to GLS inhibition when ENO1 function is impaired." (PMID 26734996, 2016).
glioblastoma (36 papers, 2013 to 2026). The most malignant astrocytic tumor (WHO grade IV). "Total glutathione is a reliable biomarker of glioblastoma oxidative status steadily associated to both GLS silencing and GAB overexpression." (PMID 33610185, 2021). "MiRNA-1246, miRNA-1260a, miRNA-146a-5p, and miRNA-21-5p have been characterized as strong biomarkers of glioblastoma proliferation linked to both GLS silencing and GAB overexpression." (PMID 33610185, 2021). "Prior research showed that blocking the Notch pathway suppressed GLS expression and resulted in reducing intracellular glutamate levels in glioblastoma cells." (PMID 38169546, 2024). "The combination of PP242, a mTORC1 inhibitor, in combination with GLS inhibition (compound 968) in glioblastoma blocked tumor growth in tumor-bearing mice demonstrating that GLS inhibition reverses mTORC1- targeted therapy resistance." (PMID 38139462, 2023). "Although compound 6 is considered a promising lead, further pharmacological and biological studies are required to fully disclose the mechanism of action of glutaminase inhibitor 6 in glioblastoma cells." (PMID 36831355, 2023). "The inhibition of GLS by BPTES in glioblastoma cells decreases glutamate, and α-KG levels, and reduces the growth of mutant IDH1 cells compared to those expressing wild-type IDH1." (PMID 38139462, 2023). "Still, the development of glutaminase inhibitors is limited, which demands the identification of novel inhibitors for disrupting glioblastoma metabolism and its progression." (PMID 36831355, 2023). "Here, we report a novel library of dioxocin derivatives as glutaminase inhibitors and their pharmacological intervention for treating glioblastoma." (PMID 36831355, 2023). "For example, Cheng at al studied metabolic reprogramming in two glutamine-dependent glioblastoma (GBM) cell lines in response to glutaminase knockdown." (PMID 33808495, 2021). "Our observation is further supported by reports showing the effect of an LXR agonist, LXR623, on partially increased glutamine metabolism in glioblastoma cells and identifying GLS as an LXR target in macrophages." (PMID 33348693, 2020). "One study also reveals that glutaminase (GLS) and glutamate levels are elevated in glioblastoma after treating with mTOR inhibitor." (PMID 31277692, 2019). "Silencing of GLS significantly decreased proliferation of prostate cancer cells in vitro, Ehrlich ascites tumor cells in vitro and in vivo, and T98G glioblastoma cells." (PMID 24096582, 2014). "In conclusion, the key finding of this study is that GLS silencing reduces proliferation and viability of glioblastoma cells and strengthen the antiproliferative effect evoked by GLS2 overexpression." (PMID 24096582, 2014). "Therefore, the silencing of GLS or the inhibition of GA activity suppresses glioblastoma cell survival and growth." (PMID 39259492, 2024). "In glioblastoma, GLS is commonly overexpressed and considered pro-oncogenic." (PMID 36672480, 2023). "For example, zaprinast is a strong glutaminase inhibitor that may decrease the abnormally high levels of D-2-hydroxyglutarate in glioblastoma cells." (PMID 34575827, 2021). "The diminishing expression or activity of GLS isoforms significantly decreased the proliferation of the prostate cancer cells, leukemic cells, Ehrlich ascites tumor cells, breast cancer cells, and glioblastoma cells." (PMID 30669455, 2019). "Likewise, human glioblastoma T98G cell line expresses high amounts of GLS transcripts, while GLS2 transcripts are hardly detectable in these cells." (PMID 24096582, 2014). "Using the clinically approved GLS inhibitor CB-839 (Telaglenastat), we found significant changes in glutamine metabolism, including both the oxidative and reductive fates of Gln-derived alpha-ketoglutarate in the tricarboxylic acid cycle, in three glioblastoma cell lines." (PMID 36672480, 2023). "In glioblastoma (GBM), the most aggressive brain tumor, GLS is highly expressed and in most cases GLS2 is silenced." (PMID 30669455, 2019).